IFIT1 (interferon induced protein with tetratricopeptide repeats 1)
Diseases named in the same sentence as IFIT1 in open-access papers (continued):
Sharing a sentence is not in itself a finding about the gene and the disease.
infection (continued). "Our studies show that the majority of the ~100 upregulated genes in infected HFFF cells at 4 hours were classified as ISG transcripts, with at least two of these (IFIT1 and IFIT2) shown by our more detailed studies to be activated between two and four hours after infection." (PMID 30475899, 2018). "Similarly, mOasl2 significantly enhanced the expression of RNase L and six (IRF3, IFNα, IFNβ, IFIT1, IL8, and TNFα) of 10 tested genes related to IFN signaling in A549 cells after infection by the PR8 virus." (PMID 29973937, 2018). "Expression of the interferon‐stimulated genes (ISGs) Ifit1, Ifi44 and Oasl1 was increased upon infection and was not altered in cells expressing ZBP1." (PMID 28716805, 2017). "Infection of Irf3-/- mice confirmed an impairment in Mx1 and Ifit1 but not Tnf induction suggesting that IRF3 is critically involved in K. pneumoniae-elicited type I IFN production in vivo." (PMID 29112952, 2017). "Along with IFIT2, IFIT1 and IFIT3 were also increased following infection with both strains." (PMID 29085037, 2017). "To examine whether AIM2 can affect expression of signal components downstream of STING, we used qPCR to monitor the mRNA expression of IFN-β and IFIT1 and ELISA to test the protein expression of IFN-β in BMDMs 24h post-infection." (PMID 27409673, 2016). "Thus, following infection of cells in an IFN-induced antiviral state, IFIT1 restricts PIV5 replication." (PMID 27512068, 2016). "The selected targets included genes that were differentially expressed in both gt1‐ and gt3‐infected samples versus controls (CXCL9, IFIT1, ISG15 and RSAD2), as well as genes that were differentially regulated only in gt1 infection (USP18) or gt3 infection (IDO1)." (PMID 25800823, 2015). "Moreover, many genes exhibited different levels of expression of the various isoforms under infection with one PRRSV strain vs. the other (PARP14, SOCS1, IFIT1, MX1, IFOTM1, RNASEL, PIKSCD and TLR3)." (PMID 24643046, 2014). "Upon infection with WT EMCV, induction of Ifit1 and Ifnb1 was limited." (PMID 24550253, 2014). "To verify that C6 and K7 impaired IFN-β, TNF-α, MIP-1α and IFN-β-dependent gene expression in innate immune cells, we infected human moDCs with 1 PFU/cell of MVA-WT, MVA-B, MVA-B ΔC6L and MVA-B ΔC6L/K7R and measured IFN-β, TNF-α, MIP-1α, IFIT1 and IFIT2 mRNA levels 6 h post-infection." (PMID 23826170, 2013). "Heavy/light ratios of cellular proteins were comparable in Ifit1+/+ and Ifit1−/− MΦs, irrespective of the virus used for infection, suggesting that neither the presence of Ifit1 nor infection with MHV-DA affected the overall rate of translation in the cells." (PMID 24098121, 2013). "In contrast to the control cells, treating CPI−-infected Hep2/BVDV-Npro/shISG56/IFIT1 cells with IFN either prior to or after infection did not significantly alter either the pattern or levels of virus transcript accumulation." (PMID 23052390, 2013). "In summary, our results show that Ifit1 restricts infection in vivo of WNV lacking 2′-O methylation of the 5′ cap structure, as targeted Ifit1 gene deletion was associated with enhanced replication of WNV-E218A in mice." (PMID 22589727, 2012). "Ex vivo infection experiments revealed impaired infectivity of WNV-E218A in both wild type and Ifit1−/− BMEC, which are a major component of the BBB and are hypothesized to contribute to WNV entry into the CNS." (PMID 22589727, 2012). "We also cannot exclude the possibility of a transient difference in BBB permeability of Ifit1−/− mice induced specifically by peripheral infection of WNV-WT but not WNV-E218A." (PMID 22589727, 2012). "Based on tissue and region-specific effects in vivo, and infection of primary cells ex vivo, we postulate a model in which distinct cell types differentially use Ifit1 to inhibit infection of WNV-E218A, and likely other viruses, lacking 2′-O methylation." (PMID 22589727, 2012).
infection (continued). "This response in Ifit1−/− mice nonetheless failed to control infection and/or contributed to lethality by inducing immunopathology." (PMID 22589727, 2012). "Notably, while stimulation with synthetic dsRNA induced IFIT1 expression, no induction was observed following infection with VSV-GFP nor MERS-CoV." (PMID 40233033, 2025). "Following RSV-L19 infection (MOI = 10) of sh-ARCN1-RAW264.7 cells for 12 h, RT-qPCR analysis revealed significantly increased mRNA levels of Ifnb1 and interferon-stimulated genes Isg15 and Ifit1 compared to sh-NC-RAW264.7 controls, suggesting that ARCN1 suppresses RSV-induced IFN-β signaling." (PMID 41343552, 2025). "Nevertheless, infection of LSDV did not result in the decrease of IFIT1." (PMID 40096184, 2025). "Also, it was important to discuss thatthough our study identified a total of 9 genes that were common among three stages, but only 6 of them (OASL, IFI27, IFIT1, IFIT3, RSAD2and IFI44L) made into the PPI network whose expression level increases with the increase in the level of infection." (PMID 40255307, 2025). "Similarly, IFIT1 is an effector molecule that limits viral translation, and limits infection of viruses lacking RNA 2′-O methylation by binding to mRNAs lacking RNA 2′-o methylation." (PMID 38737277, 2024). "Indeed, infection of parental A549 cells with PR8-NS1(N80) mutant virus resulted in lower accumulation of PA protein and higher induction of IFN-stimulated genes IFIT1 and ISG15 compared to infection with the WT virus at the same multiplicity of infection (MOI)." (PMID 38629840, 2024). "These abortive infections failed to induce IFIT1 expression." (PMID 37814072, 2023). "To evaluate whether infection of LMECs induced an antiviral immune response, we inoculated LMECs with pH1N1, H1N1, or H3N2 virus and measured RNA expression of IFN-β, IFN-λ and interferon-stimulated gene (ISG) IFIT1 24 hpi." (PMID 37072183, 2023). "Notably, even at the final timepoint (16 hours post infection (h.p.i.)), after which we observed cell death of EMCV-infected cells, less than half of infected cells showed IFIT1 expression, indicating heterogeneity of the antiviral response following 5xSunTag-EMCV(LZn) infection." (PMID 37814072, 2023). "The results demonstrated that both the mRNA and protein levels of IFIT1 and IFIT2 were increased in rIBV-ΔPL1pro-N infected cells at 16 and 20 h post-infection to different degrees, indicating that the N-terminal region of PL1pro affects the expressions of ISGs during later stages of infection." (PMID 38087313, 2023). "SARS-CoV-2-Δ8 infection showed a trend of increasing IFN signaling (IFNλ3, interferon-stimulated gene [ISG15], and MX1, P values 0.4337, 0.1126, and 0.2285, respectively) as compared to WT at 3 dpi, while reducing IFN-stimulated gene levels (IFNλ3, ISG15, IFIT1, OAS1, and XAF1) at 6 dpi." (PMID 37623322, 2023). "Indeed, the individual silencing of IFIT1, 2 and 3 was reported to increase IAV replication, as measured by a viral PolI reporter expression system after infection, suggesting the IFIT1/2/3 heterotrimer complex could be responsible for this antiviral activity." (PMID 33810083, 2021). "Thus, we next measured expression of several ISGs, including Isg15, Ifit1 and Mx1, over the same time course in BMDMs in addition to RAW 264.7 macrophages and observed significant induction of these genes 4h post-infection with higher induction at 8h in both cell types." (PMID 34473814, 2021). "Additionally, the upregulation of IFNβ-1, INFλ-1, -2, -3 and IFIT-1, -2, -3, following apical and basolateral infection was noted." (PMID 32872518, 2020). "However, upon infection of the knockout lines with HTNV, we observed delay in HTNV-induced innate immune activation in the RIG-I-/- compared to MDA5-/- and Cas9, evidenced by delayed IFIT1 and MX protein and gene expression." (PMID 32330200, 2020).
infection (continued). "In contrast, siRNA disruption during infection reduced the expression of viral sensor genes RIG-I and MDA5, possibly leading to the downregulation of downstream responders of IFN induction such as IFN-β, MxA, OAS1, and IFIT1 (Interferon-Induced Protein with Tetratricopeptide Repeats 1)." (PMID 32899429, 2020). "Notwithstanding the possibility that some of our siRNAs might have induced off-target effects, the ensemble of our findings suggest that all three IFIT proteins, but especially IFIT1, are able to restrict KSHV lytic protein expression during reactivation and/or de novo infection." (PMID 31059555, 2019). "We show that the expression of the interferon-stimulated proteins MX1, IFIT1, IFIT3 and ISG15, as well as expression of defense response proteins DDX58, STAT1, OAS3, EIF2AK2 and SAMHD1 was significantly up-regulated in these cells upon infection with either virus." (PMID 30959732, 2019). "Since knockout of Ifit1 promoted MNV replicationin vitro, this suggests that Ifit1 may restrict MNV replication directly, by inhibiting viral translation, or indirectly, by creating a cellular environment which is less permissive to infection." (PMID 31372503, 2019). "Although Isg20−/− mice were not more susceptible to infection with wild-type (WT) pathogenic strains of CHIKV or VEEV, an IFIT1-sensitive mutant of VEEV was more virulent in Isg20−/− mice and replicated to higher levels in some, but not all, Isg20−/− primary cells than in the WT counterparts." (PMID 30232164, 2018). "Combined with our understanding of IFN-mediated ISG20 upregulation and ISG20-mediated upregulation of IFIT1 and other antiviral effectors in vitro, the mouse model of VEEV-G3A suggests a feed-forward mechanism by which ISG20 amplifies IFN and ISG production in response to infection." (PMID 30232164, 2018). "Similarly, ISGs (IFIT1–2, GBP1, OASL) have been detected in MDMs 6 h post in vitro infection with ZEBOV-Mayinga (EBOV strain isolated in 1976) in the absence of increased IFNα/β expression." (PMID 29123522, 2017). "MHV-WT grew to high titres in the spleens of infected Ifit1+/+ mice, whereas no viral replication could be detected upon infection with MHV-DA." (PMID 24098121, 2013). "Like its specific antiviral activity, this property of IFIT1 may only become apparent during infections with viruses that produce non-methylated RNA 5′ ends." (PMID 24098121, 2013). "However, IFIT1 over-expression did not completely block E217A infection nor did it affect virus output from the infected cells, suggesting that other IFN-mediated signals are involved in the response against DENV." (PMID 23935499, 2013). "Specifically, suppression of IFI6 and OAS1 was impaired by HAdV-B7 when RuvBL2 was knocked down, but not of IFIT1 nor IFIT2, while only OAS1 expression in HAdV-B14 infection was affected by RuvBL2 knockdown." (PMID 38940561, 2024). "Similar to the lab-adapted strains, we observed six ISG-related DAPs (IFIT1, IFIT2, IFIT3, OAS3, ISG15, and MX1) significantly upregulated compared to MOCK infected UNOs, upon infection with clinical isolates of PeV-A3, but not PeV-A1." (PMID 38514653, 2024). "When infecting THP-1-IFIT-1-Gluc cells, no activation of the IFIT-1-Gluc reporter was observed upon either parental or VACV.ΔB2 infection, although a small but reproducible difference between the viruses was observed." (PMID 39431915, 2024). "The data indicated that single treatment with Pte or Pin during EV-D68 infection did not influence intrinsic innate immune status, as there were no observable changes in the expression of IFN-α, IFN-β, IFIT1, or MX1." (PMID 36845118, 2023). "Unlike IFIT1 and IFIT2, IFIT3 showed only a slight increase in citrullination during infection, which was not statistically significant (p = 0.06)." (PMID 38055760, 2023).
infection (continued). "We did not detect any IFNB1+ cells upon 5xSunTag-EMCV(LWT) infection, indicative of the potent antagonism exerted by the L protein and illustrating the benefit of using EMCV(LZn) mutant virus and IFIT1 as a reporter gene in studying antiviral responses." (PMID 37814072, 2023). "HIV-Luc IND116A infection of siNT control cells resulted in low but significant induction of ISG15, IFIT1, and IFIT2 compared to that in noninfected control cells." (PMID 37922361, 2023). "SARS-CoV-2 induced phosphorylation of STAT1, as well as rapid IFIT1 and OAS2 mRNA induction, suggest a similar host response to SARS-CoV-2 as that observed during mutant MERS-CoV-ΔNS4ab infection, and not that of WT MERS-CoV infection." (PMID 33811184, 2021). "The A549 cells lacking the XRN1 protein showed increased IFN-β, IFIT1, IFIT3, and ISG15 expression compared with the A549 control cells at 4 to 8 h after WSN infection." (PMID 34311580, 2021). "(B) Fold induction of IFIT1-Luc after activation of STING by cGAMP (5 μg/ml) and infection with VLP bearing WT or mutant Vpr, or lacking Vpr (1 RT U/ml) in IFIT1-Luc reporter THP-1 cells." (PMID 33300875, 2020). "An interesting finding that warrants further investigation is the observation that MAVS contributed to CXCL‐10 production in response to infection with DRV‐treated virus, but did not contribute to the corresponding IFIT‐1 reporter activity." (PMID 32852081, 2020). "(B) Fold induction of IFIT1-Luc after activation of STING by cGAMP (5 μg/ml) and infection with HIV-1 virus-like particles (VLP) lacking genome and bearing Vpr (+Vpr) or lacking Vpr (-Vpr) (1 RT U/ml) in IFIT1-Luc reporter THP-1 cells." (PMID 33300875, 2020). "Expression of eight of these genes (IFIH1, OAS2, IFIT1, IFIT2, IFIT3, IFIT5, USP18 and DDX58F) was significantly elevated in response to VSV-ΔM51 infection in permissive cells, but not in resistant PDACs." (PMID 27533247, 2016). "Twenty four host proteins (17 in the cytosol and seven in the nucleus) are up-regulated ≥1.5-fold by T3D infection but not by T1L infection, and four of these proteins (Mx1, ISG15, IFIT1, and STAT1) are up-regulated >3.5-fold by T3D." (PMID 25905045, 2015). "While Ifit1 had a marginal impact on WNV-WT pathogenesis, replication of WNV-E218A was increased in peripheral tissues of Ifit1−/− mice after subcutaneous infection, yet this failed to result in efficient spread to the brain." (PMID 22589727, 2012). "While deletion of Ifit1 had marginal effects on WNV-WT pathogenesis, WNV-E218A showed increased replication in peripheral tissues of Ifit1−/− mice after subcutaneous infection, yet this failed to correlate with enhanced infection in the brain or lethality." (PMID 22589727, 2012). "In the present study, we observed that several ISGs with known or proposed anti-CCHFV activity, i.e., Mx1, ISG15 and ISG20 or not defined for CCHFV like IFIT1, IFIT3, IFITM3, IFI16, and OAS3 were upregulated in the acute phase CCHFV patient samples as well as in the cell-infection model." (PMID 35437144, 2022). "It is noteworthy that whereas our data show a strong inhibition of IFIT-1 mRNA expression during Armenia/07 infection, in comparison with the expression during NH/P68 infection, the amount of IFN-β secreted after 8 hpi with Armenia/07 does not affect IFN-β-dependent gene IFIT-1 expression." (PMID 30918080, 2019). "However, HBVΔX infection did not induce the expression of two prototypic ISGs, RSAD2 (Viperin) and IFIT1 (ISG56), at any time point post-infection when cccDNA was transcriptionally silent (none or siCtrl)." (PMID 28095508, 2017). "Infection of the human lung epithelial cell line A549 with RSV-HD resulted in the expression of IFNL1 (also known as IL-29), IFIT1 (also known as ISG56) and IFNB1; no expression of these genes was detected upon infection with RSV-LD, despite higher levels of viral replication (RSV G expression)." (PMID 26336095, 2015).
infection (continued). "Results showing that IFIT1, IFIT2, and IFIT3, but not IFIT5, were induced with similar kinetics by DV infection suggest the possibility of co-regulation, and also the coordination and non-redundant functioning of these molecules in IFN-mediated signaling events, as observed in neurons." (PMID 24223959, 2013). "Whereas Ifit1−/− DC and GCN sustained enhanced infection of WNV-E218A, Ifit1−/− MEF and CN showed smaller increases in infection, and no increase in WNV-E218A replication was observed in Ifit1−/− BMEC." (PMID 22589727, 2012). "Although all Ifit1−/− mice succumbed to infection regardless of treatment, depletion of CD8+ T cells delayed the mean time to death by 3 days (P<0.001), suggesting a pathologic effect of these cells in Ifit1−/− mice." (PMID 22589727, 2012).